TRA2A (transformer 2 alpha homolog)
Description:
Sequence-specific RNA-binding protein which participates in the control of pre-mRNA splicing.
Synonyms: htra-2-alpha; AWMS1; HSU53209
Tractability: PROTAC: UniProt records ubiquitination sites on it; ubiquitination databases record sites on it; its protein half-life has been measured.
Gene: Protein-coding gene on chromosome 7 (23,504,780 to 23,532,041, reverse strand). Ensembl gene ENSG00000164548.
Subcellular location: Nucleus
Subcellular location (Human Protein Atlas): Nucleoli; Nucleoplasm; Vesicles
Gene Ontology:
Molecular function: protein binding; RNA binding; nucleic acid binding
Biological process: mRNA splicing, via spliceosome
Cellular component: nucleolus; nucleoplasm; nucleus; spliceosomal complex
Genetic constraint (gnomAD): Loss-of-function variants: 25 observed, 35.68 expected, observed/expected ratio (o/e) 0.7, 90% interval 0.51 to 0.98. The upper end of that interval is the gene's LOEUF score, 0.98, which puts it in group 4 of 6, group 1 being the genes least tolerant of losing a copy. Missense variants: 262 observed, 345.07 expected, observed/expected ratio (o/e) 0.76, 90% interval 0.69 to 0.84. Synonymous variants: 117 observed, 117.95 expected, observed/expected ratio (o/e) 0.99, 90% interval 0.85 to 1.16.
Homologues: Orthologues: chimpanzee TRA2A (100% identical), guinea pig TRA2A (100% identical), macaque TRA2A (100% identical), rabbit TRA2A (99% identical), dog TRA2A (99% identical), mouse Tra2a (99% identical), pig TRA2A (99% identical), rat Tra2a (99% identical), tropical clawed frog tra2a (87% identical), zebrafish tra2a (85% identical), Caenorhabditis elegans rsp-8 (43% identical), Drosophila melanogaster tra2 (43% identical). Paralogues in human: TRA2B (70% identical).
Diseases named in the same sentence as TRA2A in open-access papers:
TRA2A is named in the same sentence as 25 diseases in open-access papers, as found by Europe PMC text mining. Sharing a sentence is not in itself a finding about the gene and the disease. The quoted sentences say what the papers report.
triple-negative breast carcinoma (5 papers, 2018 to 2022). An invasive breast carcinoma which is negative for expression of estrogen receptor (ER), progesterone receptor (PR), and human epidermal growth factor receptor 2 (HER2). "TRA2A is overexpressed in the glioma cells and triple-negative breast cancer to promote proliferation, invasion, migration, and epithelial–mesenchymal transition." (PMID 35669517, 2022). "It has been found that TRA2A can promote paclitaxel therapy and promote cancer progression in triple-negative breast cancers." (PMID 32719673, 2020). "Our results support the emergent role of the spliceosome pathway in prostate carcinogenesis with TRA2A and U2AF1: TRA2A is deregulated in different cancers such as hepatocellular carcinoma, pediatric pineal germinomas and triple-negative breast cancer (TNBC)." (PMID 29805743, 2018). "TRA2A can reduce the level of normal RSRC2 splicing product RSRC2s and increase the expression of RSRC2l, an abnormal mRNA splicing product of RSRC2, which promotes the progression of triple negative breast cancer." (PMID 35669517, 2022). "In two studies, the splicing factors PTBP1 and TRA2A were up-regulated in resistant cells and promoted resistance to gemcitabine in pancreatic cancer through AS regulation of the PKM gene, and to paclitaxel in triple-negative breast cancer through AS of RSRC2, respectively." (PMID 31943118, 2020).
breast carcinoma (4 papers, 2021 to 2025). "Other splicing factors have also been associated with PTX efficacy, such as TRA2A promoting resistance to PTX in breast cancer." (PMID 39000035, 2024). "TRA2A is highly expressed in breast cancer, glioma, and liver cancer, while PYCR2 is regarded as a prognostic biomarker in the HBV-related HCC." (PMID 35669517, 2022). "In MDA-MB-231 breast cancer cells, TRA2β binds to a poison exon in the TRA2α transcript, meaning that TRA2 upregulation can suppress TRA2α expression." (PMID 41009380, 2025).
esophageal cancer (4 papers, 2021 to 2025). A primary or metastatic malignant neoplasm involving the esophagus. "By analyzing expression profiling data, we found that TRA2A is highly expressed in esophageal cancer and is associated with disease-free survival and overall survival time." (PMID 34234858, 2021). "Functionally, we demonstrated that TRA2A is associated with proliferation and migration of esophageal cancer." (PMID 34234858, 2021). "The interaction of RBMX with splicing factors such as TRA2A and hnRNP A1 offers deeper insights into the regulatory networks governing esophageal cancer progression." (PMID 40692788, 2025). "A study showed that the knockdown of splicing factor TRA2A (transformer 2 alpha homolog) significantly reduced KIAA1429 protein expression in esophageal cancer." (PMID 39456252, 2024). "In summary, this study demonstrates an important regulatory role of TRA2A-MALAT1 interaction in esophageal cancer cells." (PMID 34234858, 2021). "TRA2A was up-regulated in esophageal cancer compared to normal tissues, and patients with high TRA2A expression had shorter disease-free survival and overall survival time." (PMID 34234858, 2021). "Together, these findings elucidated that TRA2A triggers carcinogenesis via MALAT1 mediated EZH2/β-catenin axis in esophageal cancer cells." (PMID 34234858, 2021). "Functional studies also confirmed that the interaction between MALAT1 and TRA2A plays an important role in esophageal cancer cells." (PMID 34234858, 2021). "To investigate the potential function of TRA2A in esophageal carcinoma, we constructed TRA2A over-expression vector and tested TRA2A expression efficiency in both esophageal squamous cell carcinoma cell TE1 and esophageal adenocarcinoma cell OE19." (PMID 34234858, 2021). "Investigating how RBMX influences alternative splicing and m6A methylation, particularly in relation to other RNA-binding proteins such as TRA2A, may reveal new insights into the biology of esophageal cancer and resistance to therapies like sorafenib." (PMID 40692788, 2025). "We also studied the expression characteristics of TRA2A among esophageal cancer patients." (PMID 34234858, 2021). "Together, above results suggested that TRA2A is abnormally up-regulated in esophageal cancer." (PMID 34234858, 2021). "Transformer 2 alpha homolog (TRA2A), a serine/arginine-rich splicing factor, influences methylation of lncRNAs, in particular MALAT1, in esophageal carcinoma, by forming a complex with METTL14, RBMX, and KIAA1429, another m6A writers." (PMID 39280246, 2024). "To further explore the relationship between TRA2A and MALAT1, we analyzed the RNA expression correlation between TRA2A and MALAT1 in 184 esophageal cancer samples from TCGA." (PMID 34234858, 2021). "Taken together, these results suggested that TRA2A can directly bind with MALAT1, and regulate the lncRNA expression in esophageal cancer cells." (PMID 34234858, 2021). "Thus we postulated that TRA2A regulates and activates the EZH2/β-catenin pathway by binding to MALAT1 and elevating its expression, hence promotes esophageal cancer progression." (PMID 34234858, 2021). "However, the role of TRA2A in esophageal cancer progression and the molecular regulation mechanisms have not been addressed to date." (PMID 34234858, 2021).
glioma (4 papers, 2022 to 2025). A benign or malignant brain and spinal cord tumor that arises from glial cells (astrocytes, oligodendrocytes, ependymal cells). "To this end, we performed RNA-seq following TRA2A KO in a pair of glioma cell lines that we had validated to be TRA2A-dependent and independent (LN319 and LN229, respectively)." (PMID 40367120, 2025). "Another example of aberrant expression of SFs in glioma concerns the overexpression of the splicing activator TRA2A (Transformer-2 Alpha) in high-grade gliomas (III and IV) and GBM cell lines." (PMID 39915450, 2025). "TRA2A is overexpressed in glioma tissues, enhancing the proliferation, migration, invasion, and EMT of glioma cells." (PMID 39337382, 2024).
hepatocellular carcinoma (4 papers, 2018 to 2023). A malignant tumor that arises from hepatocytes. "Although E4B is highly expressed, it hardly degrades TRA2A and PYCR2 in hepatocellular carcinoma (HCC) cells, suggesting other mechanisms exist for degradation of TRA2A and PYCR2 in the HCC cells." (PMID 35669517, 2022).
pancreatic cancer (3 papers, 2020 to 2023). "Additionally, by binding to the TRA2A promoter, HIF1α can upregulate the transcription of TRA2A, causing pancreatic cancer progression." (PMID 37564197, 2023).
prostate carcinoma (2 papers, 2017 to 2022). A carcinoma that arises from epithelial cells of the prostate gland. "High TRA2A expression is associated with prostate cancer progression." (PMID 35635094, 2022). "In contrast, GS > 7 patients showed high H3K27me3 enrichment at the TRA2A promoter compared to both the GS ≤ 7 and normal groups, suggesting its major role in prostate cancer." (PMID 28403887, 2017). "Furthermore, TRA2A appeared to be H3K27me3-enriched in all patients and could thus serve as an epigenetic marker for early prostate cancer screening." (PMID 28403887, 2017).
colorectal cancer (1 paper, 2024). A primary or metastatic malignant neoplasm that affects the colon or rectum. "Among these hub genes, HNRNPL and HNRNPH1 genes may be molecular markers for early colorectal cancer diagnosis in MSS.TRA2A and SRSF6 may play important roles in PCRC metastasis." (PMID 39023715, 2024).
esophageal squamous cell carcinoma (1 paper, 2021). Esophageal squamous cell carcinoma (ESCC) is a type of esophageal carcinoma (EC) that can affect any part of the esophagus, but is usually located in the upper or middle third. "Subsequent gain- and loss-of-function studies demonstrated that TRA2A promotes proliferation and migration of esophageal squamous cell carcinoma and adenocarcinoma cells." (PMID 34234858, 2021).
gastric cancer (1 paper, 2022). A primary or metastatic malignant neoplasm involving the stomach. "Through our study, we found that TRA2A, METTL3, ALKBH5 and TYHDC2 were significantly down-regulated in gastric cancers cells." (PMID 36003776, 2022).
lymph node metastasis (1 paper, 2022). "High TRA2A expression was associated with advanced stage, poor differentiation, and lymph node metastasis." (PMID 35635094, 2022). "Moreover, we observed that high TRA2A expression was associated with advanced stage, poor differentiation, and lymph node metastasis." (PMID 35635094, 2022).
malaria (1 paper, 2021). Malaria is a serious and sometimes fatal disease caused by a parasite that commonly infects a certain type of mosquito which feeds on humans. "Of the up-regulated genes in severe malaria, TRA2A was found to promote human influenza A virus replication by inhibiting the splicing of the NS segment of its mRNA." (PMID 34746025, 2021).
oral squamous cell carcinoma (1 paper, 2024). "In this context, our results describe for the first time the association between TRA2A and OSCC oral squamous cell carcinoma, among other splicing factors, and their relationship might unveil the role of these newly described splicing factors as therapeutic targets in OSCC." (PMID 39000035, 2024).
stomach adenocarcinoma (1 paper, 2024). "Reduced SRSF11 and TRA2A expression is positively correlated with poor survival in patients with stomach adenocarcinoma." (PMID 39678510, 2024).
tumor (14 papers, 2021 to 2026). "To individually validate TRA2A dependency, we selected a panel of TRA2A-dependent cell lines (NCI-H23, NCI-H2286, LN319, PANC0504) and tumor type-matched TRA2A-independent cell lines (A549, LN229, AsPC-1)." (PMID 40367120, 2025). "Mechanistically, lnc-ZEB2-19, as a tumor suppressor gene, inhibits the activation of NF-kappa B by interacting with TRA2A to decrease the stabilization of RSPH14 mRNA." (PMID 37564197, 2023). "TRA2A promotes paclitaxel resistance and tumor progression in TNBC via regulating alternative splicing." (PMID 34497807, 2021). "TRA2A can influence tumor progression by participating in pre-mRNA alternative splicing (AS)." (PMID 37564197, 2023). "Moreover, we found that Prkcsh, Tra2a, and Shoc2 are underexpressed at the tumor’s periphery compared to its center and mid-zones." (PMID 36151122, 2022). "Interestingly, TRA2A dependency was not specific to a particular cell or tumor type and was associated with a diverse range of cancer contexts." (PMID 40367120, 2025). "From these RBPs, only HNRNPH1 is differentially expressed between tumor core and peripheral neoplastic cells, while four RBPs (HNRNPH1, HNRNPF, TRA2A, DDX42) are reported to be differentially spliced themselves." (PMID 39936571, 2025). "Moreover, we observed that 21 splicing factor genes showed significantly differential AS between SS and tumor-adjacent tissues, such as HNRNPA1, PTBP2, QKI, RBFOX2, and TRA2A." (PMID 36118864, 2022).
cancer (11 papers, 2018 to 2025). A tumor composed of atypical neoplastic, often pleomorphic cells that invade other tissues. "gene effect of -0.07), a subset of cancer lines were highly sensitive to TRA2A loss (n = 23 lines with gene effect < -0.5)." (PMID 40367120, 2025). "We discovered that a subset of cancer cell lines are unexpectedly vulnerable to loss of just TRA2A, despite having its partner TRA2B present." (PMID 40367120, 2025). "Genomics analysis indicates an association between TRA2A expression and disease-free survival and overall survival time in cancer patients." (PMID 34234858, 2021). "Here, we identify TRA2A as a strong and selective dependency in a diverse subset of cancer cell lines." (PMID 40367120, 2025). "While loss of TRA2A alone is typically neutral due to compensation by TRA2B, we discover that a subset of cancer cell lines are highly TRA2A-dependent." (PMID 40367120, 2025). "Examining genome-wide CRISPR screening data from the Cancer Dependency Map (DepMap, 24Q2 release), we found that the splicing factor TRA2A exhibited a pattern consistent with other selective dependencies." (PMID 40367120, 2025). "Here, we uncover a unique cancer vulnerability involving the paralogous splicing factors TRA2A and TRA2B." (PMID 40367120, 2025). "In conclusion, our results demonstrate that TRA2A is a strong and selective dependency in a subset of cancer cell lines." (PMID 40367120, 2025). "In contrast, TRA2A, as an RNA-binding protein, can also be a critical and effective participator in the development of various cancers." (PMID 37564197, 2023). "In recent years, the role of TRA2A in cancer has been receiving increasing research attention." (PMID 34234858, 2021). "In addition to its canonical function as a mRNA splicing factor, TRA2A directly binds to lncRNA as an RNA-binding protein and participates in cancer signaling transduction, therefore providing new insights into mechanism and treatment." (PMID 34234858, 2021). "TRA2A is shown to express at stable level in a variety of cancer cell lines." (PMID 34234858, 2021). "Currently there are few reports on TRA2A expression characteristics in human cancer cells." (PMID 34234858, 2021). "Vertebrates have two transformer 2 homologs, TRA2A and TRA2B, and there is emerging evidence that dysregulation of the human proteins is involved in abnormal patterns of splicing observed in some cancers." (PMID 40750357, 2025). "Among these proteins, Transformer2A (TRA2A) and Pyrroline-5-carboxylate reductase 2 (PYCR2) are closely related to cancer development." (PMID 35669517, 2022). "Transformer2A (TRA2A) and Pyrroline-5-carboxylate reductase 2 (PYCR2) are related to cancer development and are overexpressed in many cancer cells." (PMID 35669517, 2022). "TRA2A and PYCR2 are highly expressed in several cancer tissues and regarded as oncogenes or biomarkers." (PMID 35669517, 2022). "Among these cancer relapse-relevant genes, METTL16, FTO, EIF3D, and EIF3I were good prognostic factors, while TRA2A, HNRNPA2B1, and YTHDC2 were bad ones." (PMID 33273988, 2020). "In addition, three other proteins analyzed in this study, HNRNPH1, TRA2A, and SRSF6, were found to be involved in cancer development in previous studies." (PMID 39023715, 2024). "Next, RNA-Seq was conducted to explore the downstream gene of lnc-ZEB2-19, and RSPH14, a gene recognized as a prognostic marker in HCC20 and NSCLC34 for the promotion of cancer progression, was selected and demonstrated to be a common target of lnc-ZEB2-19 and TRA2A." (PMID 37564197, 2023). "Since both E4B and its substrates, TRA2A and PYCR2, are highly expressed in many cancer tissues and cells, we wanted to know whether E4B can degrade TRA2A and PYCR2 efficiently in the same type of cancer cells." (PMID 35669517, 2022). "Thus, paralogs involved in the regulation of RNA splicing, such as TRA2A/TRA2B, may represent a source of particularly strong synthetic lethalities and effective therapeutic targets for cancer." (PMID 40367120, 2025).
cardiovascular diseases (1 paper, 2021). "At least 6 critical genes, namely CTNNB1, HNRNPA1, SRSF4, TRA2A, SFPQ, and RBM5, and two large clusters of biological terms which are associated with the cardiovascular diseases are deregulated in the presence of omeprazole." (PMID 34659661, 2021).
infection (1 paper, 2024). The state of being infected such as from the introduction of a foreign agent such as serum, vaccine, antigenic substance or organism. "TRA2A (transformer 2 alpha homolog), an mRNA splicing regulator, restricts the infection of avian influenza viruses but not the human influenza viruses in humans." (PMID 38392865, 2024).
TRA2A also shares sentences with these, for which no sentence is quoted: adenocarcinoma (1 paper); esophageal adenocarcinoma (1); Ewing sarcoma (1); liver cancer (1); metastatic disease (1); pineal germinomas (1); viral infection (1).